MB (myoglobin)
Diseases named in the same sentence as MB in open-access papers (continued):
Sharing a sentence is not in itself a finding about the gene and the disease.
pulmonary TB (1 paper, 2021). "When only the individuals with pulmonary TB were compared to those with ORD, significant differences were observed for SAA, CRP, VEGFR3, RANTES, Pentraxin3, Ferritin, CCL18, MPO, GDF-15, MMP-1, PDGF-BB, Procalcitonin, MDC, Myoglobin, and VCAM-1." (PMID 33732236, 2021).
pyrexia (1 paper, 2019). "Laboratory examination shows that CK will rapidly rise to a fivefold or greater elevation after onset of symptoms, accompanied with elevated CK-MB; however, the MB fraction is less than 5%, without pyrexia, liver, and kidney function damaged." (PMID 31354999, 2019).
Right ventricular hypertrophy (1 paper, 2016). In this case the right ventricle is more muscular than normal, causing a characteristic boot-shaped (coeur-en-sabot) appearance as seen on anterior- posterior chest x-rays. "We conclude that Mb mRNA expression is not increased during pressure overload-induced right ventricular hypertrophy and that the increase in myoglobin content per myocyte is likely due to increased translation." (PMID 27572699, 2016).
silicosis (1 paper, 2024). Silicosis is a respiratory disease caused by breathing in (inhaling) silica dust. "The SSc patients with silicosis had morefrequent occurrence of TB (P = 0.000), cardiac involved (P = 0.007), ILD (P = 0.043), elevated BNP (P = 0.013), elevated ESR (P = 0.005), while the incidence of telangiectasia (P = 0.007), elevated myoglobin (P = 0.009) were low." (PMID 37713025, 2024).
skeletal muscle tumor (1 paper, 2017). "Since it is a skeletal muscle tumor, it is immunopositive for HHF35, myoglobin and desmin." (PMID 27918739, 2017).
spinal cord injury (1 paper, 2023). Penetrating and non-penetrating injuries to the spinal cord resulting from traumatic external forces (e.g., WOUNDS, GUNSHOT; WHIPLASH INJURIES; etc.). "In contrast, the other research explores the creatine kinase (CK), heart-type fatty acid binding protein (H-FAB), and myoglobin (Mb) for the control and spinal cord injury (SCI) groups." (PMID 37685277, 2023).
spindle cell tumor (1 paper, 2013). "Histologically, it is described as a highly cellular spindle cell tumor with frequent mitotic activity, staining positive for desmin, myosin, myoglobin, myogenin, and myoD1 markers." (PMID 23936713, 2013).
steatosis (1 paper, 2018). Increased lipid within the cytoplasm of cells. "Chronic hind limb ischemia in mice was verified by myoglobin staining, quantification of steatosis and the number of muscle fibers." (PMID 29703251, 2018).
thrombosis (1 paper, 2024). "In addition, proteomic studies have identified MMP-7, MB, TM, and TIM-1 as biomarkers associated with atherosclerotic thrombosis and inflammation associated with OH." (PMID 38682102, 2024).
tumor (47 papers, 1989 to 2026). "Conversely, overexpression of MB in NSCLC was associated with poor prognosis, suggesting a tumor-type specific role of MB in cancer cells." (PMID 36232784, 2022). "Myoglobin (MB) is associated with tumor progression and helps to overcome hypoxia in cancer cells." (PMID 22768131, 2012). "Immunohistochemistry: the tumor cells expressed Myogenin (11/13), Desmin (13/13), MyoD1 (12/13) and Myoglobin (5/9)." (PMID 40161378, 2025). "The tumor cells showed strong diffuse cytoplasmic immunopositivity for myoglobin and vimentin, and focal staining for desmin." (PMID 37649059, 2023). "Immunohistochemistry reveals tumor cells’ reactivity to vimentin, desmin, actin, myoglobin, MyoD1, and myogenin." (PMID 36777814, 2023). "Taken together, these results indicate that Ure-MB binds to targets in both tumor and normal tissues." (PMID 35318394, 2022). "Their findings suggested an effective approach to enhance efficiency of radiotherapy by usage of genetically modified O2-bound myoglobin particles, and also showed an O2 transport function of MB in tumor cells." (PMID 34671319, 2021). "Immunohistochemically, ERMS typically express skeletal muscle markers: Tumor cells usually stain positive for vimentin, desmin, myogenin and myoglobin." (PMID 27357857, 2016). "By histochemical analysis, the tumor was shown a part of positive for desmin and myoglobin and a part of positive for synaphtophysin and vimentin." (PMID 27250580, 2016). "By contrast, decreased concentrations were observed in the case of tumor metastatic process-associated protein NM23 (spot 20), myoglobin (spot 21), the ATP synthase Atp5b (spot 22), creatine kinase (spot 23) and malate dehydrogenase (spot 24)." (PMID 23828267, 2013). "Myoglobin mRNA was found in a subset of breast cancer cell lines; in microdissected tumours Mb transcript was markedly upregulated." (PMID 20531416, 2010). "Myoglobin and cytoglobin are tumor suppressors in breast and lung tumors." (PMID 36346805, 2022). "Cystatin-B (CSTB), leukotriene A-4 hydrolase (LTA4H), protein NDRG1 (NDRG1), and phosphoglycerate kinase 1 (PGK1) from the neoplastic island dataset and collagen alpha-1(VI) chain (COL6A1), integrin alpha-V (ITGAV) and myoglobin (MB) from the tumor stromal dataset were prioritized." (PMID 30185791, 2018). "Immunohistochemically, the tumour cells were positive for vimentin, actin, desmin, and myoglobin." (PMID 22792486, 2012). "When the tumor invades the liver and causes liver cell damage, myoglobin may be released into the blood as a non-specific response." (PMID 39324006, 2024). "Therefore, the oxygen-carrying protein myoglobin (Mb) was loaded into Gd-NTs (Mb@Gd-NTs), which enabled spatiotemporal codelivery of O2 and high density of Gd-Tex into tumors, resulting in efficient relief of tumor hypoxia and the significant enhancement of Gd-Tex radiosensitization." (PMID 37794000, 2023). "No mutations in catechol-O-methyltransferase (COMT), fatty acid binding protein 4 (FABP4), myoglobin (MB) and metallothionein 2A (MT2A) were detected in COAD tumor tissues." (PMID 36203457, 2022). "Further, the tumor didn’t express desmin, ck-pan, α-smooth muscle actin, S-100, myoglobin and CD34, suggesting a dedifferentiated tumor." (PMID 33422117, 2021). "Conversely, established cancer cells engineered to over-express myoglobin, thus containing higher intracellular oxygen and lower HIF1-α levels, exhibit a decrease in xenograft tumor growth." (PMID 21589870, 2011). "In IHC examinations performed for differential diagnosis, while vimentin, smooth muscle actin, myoglobin, and positive reaction in tumor cells are expected, a negative result is obtained with factor VIII-related antigen, epithelial membrane antigen, and CD34." (PMID 33355800, 2021).
tumor (continued). "Among them, 13 proteins correlated with clinicopathological parameters and of these proteins, eight proteins were identified in neoplastic islands (ACTR2, CSTB, COL1A2, LTA4H, PGK1, NDRG1, S100A8, S100A9) and five proteins were identified in tumor stroma (COL6A1, FSCN1, ITGAV, MB, THBS2)." (PMID 30185791, 2018). "In a remaining single case, wherein MYOD1 was negative and myogenin was not performed, tumor cells were positive for myoglobin." (PMID 27562493, 2016). "Immunohistochemically, the tumor cells were widely positive for vimentin, CD56, CD99 and focally positive for synaptophysin, CD10, progesterone receptor, desmin and CD34, but negative for EMA, cytokeratin, estrogen receptor, S-100, GFAP and myoglobin." (PMID 23217062, 2012). "Immunohistochemically, the tumor cells are positive for SM-actin and desmin, but negative for myoglobin and S-100 protein; 4) Rhabdomyosarcoma, especially embryonal rhabdomyosarcoma, is composed of undifferentiated rounded and spindle cells." (PMID 22515616, 2012). "In addition, the tumor cells are negative for skeletal muscle proteins, such as desmin and myoglobin, and are positive for S-100 protein; 2) In malignant fibrous histiocytoma, the tumor is composed of spindle cells and giant tumor cells." (PMID 22515616, 2012). "However, the tumor cells do not express S-100 protein, desmin, or myoglobin, but do express AACT and CD68; 3) In leiomyosarcoma, the pattern of growth is predominantly fascicular, with the tumor bundles intersecting each other at wide angles." (PMID 22515616, 2012). "Several kinds of monoclonal antibody were used to evaluate tumor cells immunohistochemically and included anti-Vimentin, CD31, CD34, cytokeratin (CK AE1/AE3, 34 β-E 12, 5/6, and CAM 5.2), desmin, α-smooth muscle actin (α-SMA), myoglobin, myogenin, and Ki-67 (MIB-1) antibodies." (PMID 21329505, 2011). "Myoglobin did not correlate with pT stage, nodal status or tumour type." (PMID 20531416, 2010). "At the same time, cardiac rhabdoid tumor cells were positive by PAS staining and specifically expressed rhabdoid characteristic actin, desmin, myoglobin, and other immunohistochemical markers but did not express ki-67." (PMID 36337871, 2022). "In contrast, Myoglobin, a differentiated striated muscle marker was usually not expressed in SRMS, indicating the primitive status of the tumor cell." (PMID 23379991, 2013). "Immunostaining showed that the tumor was strongly positive for Vimentin, Desmin and MyoD1, and was negative for CK, P63, NSE, CD45, CD30, S-100, CD99, Myoglobin, CD68, CD34, CD31, α–SMA." (PMID 23379991, 2013). "Immunostaining showed that the tumor was positive for the Vimentin, Desmin and MyoD1, and was negative for CK, P63, NSE, CD45, CD30, S-100, CD99, Myoglobin, CD68, CD34, CD31, and α–SMA." (PMID 23379991, 2013). "The diagnosis was initially suspected to be adult rhabdomyoma, but the tumor cells were negative for immunostaining of desmin, muscle actin (HHF35), α-smooth muscle actin (α-SMA) and myoglobin and positive for periodic acid-Schiff with diastase (PAS-D)." (PMID 21299893, 2011). "All tumor cells showed strong positive reactivity for vimentin and negative reactivity for CD31, CD34, and myoglobin." (PMID 21329505, 2011). "The initial diagnosis was ruled out by immunohistochemical analysis that showed that tumor cells were negative for desmin, HHF35, α-SMA and myoglobin and positive for PAS-D." (PMID 21299893, 2011). "However, recent immunochemistry studies have provided better evidences of the origin of this tumor which show positive for S-100 protein, neuron-specific enolase, and CD68 but negative for muscular markers such as myoglobin, keratin, and desmin." (PMID 27068886, 2018). "Immunohistochemically, the tumor cells were widely positive for vimentin, CD56, CD99 and focally positive for synaptophysin, CD10, progesterone receptor, desmin and CD34, but negative for EMA, cytokeratin, estrogen receptor, S-100 and myoglobin." (PMID 23217062, 2012).
tumor (continued). "In Prostatic stromal sarcoma (PSS) unlike the PES, immunohistochemically, the tumour cells are widely positive for vimentin, CD56, CD99 and focally positive for synaptophysin, CD10, progesterone receptor, desmin and CD34, but negative for EMA, cytokeratin, estrogen receptor, S-100 and myoglobin." (PMID 23886403, 2013).
cancer (25 papers, 1989 to 2025). A tumor composed of atypical neoplastic, often pleomorphic cells that invade other tissues. "The MB gene encodes myoglobin, an oxygen−binding hemoprotein, which was reported to be ectopically expressed in different human cancer cell lines and cancer tissues." (PMID 36275701, 2022). "We used myoglobin (MB) as a muscle marker that was noted in the spatial transcriptomic analysis to stain the surrounding muscle compared with the cancer in the immunofluorescent images." (PMID 37370820, 2023). "MB and other globins have been proposed as potential therapeutic targets in solid tumors and cancer cells." (PMID 36223378, 2022). "Here, we confirm findings of other investigators that MB protein is expressed in a wide variety of cancers and we also report MB expression in some benign tumors, cancer-adjacent normal tissues, hyperplastic tissue samples and normal brain tissue." (PMID 33996536, 2021). "Myoglobin (MB) is a cytoplasmic, oxygen-binding heme-protein mainly found in cardiac myocytes and skeletal muscle fibers These genes are often up regulated in cancer and correlate with a poor clinical outcome where it functions as a mobile oxygen reservoir." (PMID 34671319, 2021). "In summary we show that MB protein is expressed in a wide variety of cancers, benign tumors, cancer-adjacent normal tissues, hyperplastic tissue samples and normal brain tissue." (PMID 33996536, 2021). "Hemin, a metabolite of myoglobin produced after meat intake, has been demonstrated to be involved in the cancer initiation phase." (PMID 33187129, 2020). "Myoglobin (MB) is not only strongly expressed in myocytes, but also at much lower levels in different cancer entities." (PMID 26559958, 2015). "Myoglobin (MB), present at high concentrations in striated skeletal and heart myocytes, has recently also been detected at lower expression levels in a variety of cancer specimen." (PMID 26559958, 2015). "In addition to myocytic expression, MB protein was reported to occur ectopically in different cancer types including colon cancer, osteosarcoma, leukemic bone marrow, non-small cell lung cancer, and breast cancer." (PMID 37161046, 2023). "In addition, MB knockdown caused higher levels of HIF-1α protein after treatment with NO, which also plays an important role in cancer cell survival." (PMID 34671319, 2021). "Myoglobin (MB) is increasingly recognized as a key player in cancer growth and metastasis." (PMID 33996536, 2021). "Additionally, although Gef has previously been shown to alter gene expression, mainly in studies involving cancer cell lines, ours is the first report of Gef-induced changes in the expression of cardiac transcripts, including myoglobin (Mb)." (PMID 24901703, 2014). "Further studies in larger series of patients are warranted to elucidate this question and determine the specific role of those cancer associated genes (INPP5A, CDX1, MB, CAMK2A, APOL6 vs. VPS53, FAM57A, GEMIN4, SFRS13, ELP2P, GLOD4, CSF2RA and IL3RA), differentially altered in both groups of tumors." (PMID 21811587, 2011). "However, recent studies have shown that myoglobin can be expressed in non-muscle tissues, including cancer cells." (PMID 41378098, 2025).
myopathy (17 papers, 2012 to 2025). A disease of the muscle in which the muscle fibers do not function properly. "Given her underlying myopathy, she was at an elevated risk for treatment-related complications, requiring regular monitoring of serum creatine kinase, myoglobin, and aldolase levels throughout her treatment course." (PMID 41209931, 2025). "Twelve impalas from GFs and one from a zoo (7%, 13/187) with myopathy had acute renal tubular degeneration and/or necrosis associated with intraluminal accumulations of red granular pigment consistent with myoglobin." (PMID 32787424, 2020). "Inflammatory myopathies present with muscle weakness, cardiac involvement, and laboratory findings including elevated serum creatinine kinase and elevated myoglobin levels in both urine and serum." (PMID 34437031, 2021). "Another crucial molecule, the myoglobin, is a reservoir of oxygen during muscular exercise and increases in myopathies and in vigorous exercise." (PMID 32397320, 2020). "Besides myoglobin, the list also included familiar proteins such as LDH and Tropomyosin alpha and included proteins that have been associated with other myopathies in TTN, MLIP and BIN1." (PMID 40110646, 2025). "Clinical evidence of this type of myopathy may be accompanied by elevated levels of creatinine kinase and myoglobin." (PMID 39070481, 2024). "Increased iron might partly be a consequence of hemorrhagic lesions, the common characteristics of WB myopathy, or the high myoglobin content of WB muscle." (PMID 33276466, 2020). "In contrast, resistin levels correlated neither with the creatine kinase and myoglobin levels nor with the MMT8 score in patients with inflammatory myopathies." (PMID 22577940, 2012). "It is likely that the storage temperature (2 °C ± 0.5 °C) was not enough to prevent the oxidation of myoglobin of the meat, which may have influenced the decrease in a * value on the inner surface of chicken breast affected by the myopathy when compared to normal chicken meat." (PMID 34209022, 2021). "Although macroscopic lesions are often not very evident, histopathologic findings in capture myopathy may include areas of necrosis in the CNS, lung, liver, intestine, pancreas and lymph nodes; acute skeletal and cardiac myodegeneration; and tubular nephrosis often with intratubular myoglobin casts." (PMID 30289951, 2018).
nephropathy (14 papers, 2016 to 2025). A nonspecific term referring to disease or damage of the kidneys. "Iron, serving as a core constituent of hemoglobin and myoglobin, exhibits metabolic dysregulation that functions as an inflammation marker associated with chronic diseases, and chronic inflammatory states demonstrate a potential inverse relationship with the risk of renal diseases." (PMID 40610956, 2025). "Studies have placed it above myoglobin in terms of diagnostic value, but recognize its poor specificity in patients with multiple comorbidities such as kidney disease, non-cardiac surgery, chest trauma, muscle disorders, hypothyroidism, hypoventilation, and pulmonary embolism." (PMID 33238444, 2020). "As myoglobin is recognized as being nephrotoxic, it is possible that repeated exposure to significant levels would have a cumulative effect and that such exposure might contribute to the high incidence of renal disease seen in greyhounds (D. Fegan, personal communication, 2013)." (PMID 27446941, 2016).
cardiovascular disease (13 papers, 2012 to 2025). "Commonly used biomarkers, such as high-sensitivity troponin, C-reactive protein, troponin I or troponin T, creatine kinase, B-type natriuretic peptide, and myoglobin, are essential for monitoring and treating cardiovascular diseases." (PMID 39328401, 2024). "In the case of cardiovascular diseases, markers in the blood, such as myoglobin, C-reactive protein, l-homocysteine and thrombin have been used to select DNA aptamer for the diagnosis of related diseases." (PMID 26610462, 2015). "Myoglobin increases after acute myocardial infarction, which is an important early marker in urgent diagnosis of cardiovascular diseases." (PMID 26610462, 2015). "A recent study evaluating the use of salivary biomarkers to diagnose cardiovascular disease reported that some biomarkers, such as C-reactive protein, creatine kinase-myocardial band, myoglobin, and troponin I, showed significant promise in diagnosing the condition." (PMID 39685509, 2024). "Among the 10 cardiovascular disease markers tested, 7 showed significant differences between groups (D-dimer, GDF-15, myoglobin, sICAM-1, MPO, P-selectin and lipocalin-2/NGAL)." (PMID 36163447, 2022). "The detection of myoglobin (Myo), cardiac troponin I (cTnI), creatine kinase-MB (CK-MB), and b-type natriuretic peptide (BNP) plays a vital role in diagnosing cardiovascular diseases." (PMID 25585711, 2012). "Inflammation goes hand in hand with the atherosclerotic process, which is important key event of endothelial damage.C-reactive protein (CRP), myoglobin (MYO), creatinine kinase myocardial band (CKMB), cardiac troponins, and myeloperoxidase aresalivary markers of cardiovascular diseases." (PMID 37693919, 2022).